PTGS2 (prostaglandin-endoperoxide synthase 2)
Diseases named in the same sentence as PTGS2 in open-access papers (continued):
Sharing a sentence is not in itself a finding about the gene and the disease.
periodontitis (31 papers, 2010 to 2025). An acute or chronic inflammatory process that affects the tissues that surround and support the teeth. "PTGS2 promoter methylation in periodontitis was found to be increased by five-fold, and its level was inversely associated with PTGS2 transcription." (PMID 38247810, 2024). "In a survey involving 60 patients with chronic periodontitis and 60 control subjects, the levels of PTGS2 in plasma samples were measured." (PMID 40857330, 2025). "The results indicated a statistically significant elevation in plasma PTGS2 concentration in patients with periodontitis compared to the control group (p = 0.001)." (PMID 40857330, 2025). "To further explore the potential KEGG pathways in which these genes are involved in the shared pathogenic mechanisms of AAA and periodontitis, we performed GSEA on IL1B, PTGS2, and SELL." (PMID 40857330, 2025). "The results showed reduced expression of GPX4 in both the gingiva and alveolar bone by immunofluorescence staining, consistent with a lower gingival Gpx4 level and higher Acsl4 and Ptgs2 levels by RT‒qPCR in the periodontitis group." (PMID 38670955, 2024). "PTGS2 is specifically expressed in periodontitis and plays an important role in inflammation of gingival tissue as well as alveolar bone destruction." (PMID 38139216, 2023). "Alteration of the promoter region of the protein-coding gene prostaglandin-endoperoxide synthase 2 (PTGS2) has also been shown in the event of chronic periodontitis." (PMID 34209817, 2021). "Thus, by elucidating the interplay between the identified biomarkers (IL1B, PTGS2, and SELL) and immune cells (Tregs and neutrophils), a more comprehensive comprehension of the potential comorbid mechanisms underlying AAA and periodontitis can be attained." (PMID 40857330, 2025). "In addition, polymorphisms in the PTGS2 gene encoding COX-2 and alterations in the methylation levels in the PTGS2 promoter have been linked to periodontitis." (PMID 40178270, 2025). "Comparing the Average global expression profile of neutrophils from healthy PDL versus neutrophils from PDL with periodontitis revealed increased expression of genes such as Il1b, Il1rn, Cebpb, Colec12, Ptgs2, Zfp36, Egr1, Atf3, Csf1, and Lars2 in periodontitis." (PMID 39588378, 2024). "Thus, we suggested that PTGS2 might play a critical role in periodontitis progression involving in TCR signaling pathway via interacting with FOSB." (PMID 26334995, 2015). "In our study, IL1B, PTGS2, and SELL were significantly upregulated in both AAA and periodontitis compared to the control group." (PMID 40857330, 2025). "In conclusion, we identified IL1B, PTGS2, and SELL as key interacting genes in AAA and periodontitis through machine learning and various bioinformatics analysis methods, along with the significant roles of Tregs and neutrophils." (PMID 40857330, 2025). "The hub genes identified in the periodontitis comorbidity network, such as TNF, IL6, PTGS2, IL10, and NOS3, play pivotal roles in connecting periodontitis with various systemic diseases, as indicated by their high connectivity degrees." (PMID 39337647, 2024). "PTGS2 can convert arachidonic acid into PGH2, which further synthesizes PGE2 to regulate the inflammatory response of periodontal tissues in periodontitis." (PMID 38139216, 2023). "It was discovered through network graph analysis that targets such as PTGS2, BCL2, AKT1, and CASP3 are the main targets of the Asarum–Angelica drug pair in the treatment of periodontitis." (PMID 38139216, 2023). "It is predicted that PTGS2 and BCL2 are the most important targets of the Asarum–Angelica drug pair for regulating periodontitis, and AKT1, CASP3, BAX, RELA, etc., are also relatively important targets." (PMID 38139216, 2023).
periodontitis (continued). "The group showed that periodontal therapy was correlated with alterations of PTGS2 gene methylation in patients with CP, while DNA methylation levels of TNF and IFNG remained unchanged in the periodontitis group after periodontal therapy." (PMID 32867386, 2020). "Among gene promoters analyzed in more than one study, the results were consistent only in the case of PTGS2 and STAT5A, showing increased and decreased methylation in periodontitis patients, respectively." (PMID 33256844, 2020). "Furthermore, a hypermethylation pattern of the prostaglandin-endoperoxide synthase 2 (PTGS2) promoter was found associated with reduced PTGS2 transcription, consistent with a dampening of cyclooxygenase- expression that had been reported in gingival samples collected from sites with periodontitis." (PMID 33343358, 2020). "IL6, IL6R, IFNG, PTGS2, SOCS1, and TNF were identified as candidate genes that have been assessed for DNA methylation in periodontitis." (PMID 32867386, 2020). "F. nucleatum increases the production of PTGS2, PGE2, and the ratio of RANKL/OPG in periodontal ligament (PDL) cells, which play key roles in the inflammation and destruction in periodontitis." (PMID 31921705, 2019). "In conclusion, this study identified several genes (CTSS, PLEK, IRF-8, PTGS2 and FOSB) that involved in the development and progression of periodontitis." (PMID 26334995, 2015). "A hypomethylation of signal transducers and activators of transcription 5 (STAT5) promoter and prostaglandin-endoperoxide synthase 2 (PTGS2) promoter, increased methylation at two CpG sites of TNF-α and TLR2 gene in gingival tissues from chronic periodontitis patients has been reported." (PMID 38130504, 2024). "PTGS2, namely, cyclooxygenase 2 (COX-2), could be induced and act on arachidonic acid to form prostaglandins (PGs), which are pivotal in the pathogenesis of periodontitis." (PMID 31608279, 2019). "This study identified genes (CTSS, PLEK, IRF-8, PTGS2, and FOSB) that may be involved in the development and progression of periodontitis." (PMID 26334995, 2015). "PRKCQ-AS1, has not been studied in periodontitis, and our analysis showed that PRKCQ-AS1 may act as sponge of miR-141, miR-6512, miR-513c, and regulate the expression of CXCL1, PTGS2 (COX-2), THBS1 and PRKCQ." (PMID 36045361, 2022).
bladder cancer (30 papers, 2011 to 2025). "Recent studies have shown that human bladder cancer is associated with increased expression of PTGS2." (PMID 35656081, 2022). "Along this line, patients with bladder cancer treated with aspirin, an inhibitor of cyclooxygenase (COX) 1 and 2 (encoded by PTGS1 and PTGS2, respectively), while undergoing intravesical immunotherapy benefited from better response rates." (PMID 39114912, 2024). "Compared with normal bladder tissue, the level of PTGS2 in the bladder tissue of patients with cystitis or bladder cancer is increased." (PMID 35656081, 2022). "Bladder cancer patients with stable or progressive disease (SD/PD, n = 230) exhibited a significantly higher PTGS2 gene expression when compared to patients demonstrating complete or partial response (CR/PR, n = 68) (p = 0.03)." (PMID 35347124, 2022). "From our data, the mRNA expressions of PPARG and PTGS2 were up-regulated in two bladder cancer cell lines in comparison with the normal cells SV-HUC-1." (PMID 35656081, 2022). "Disease enrichment analysis from the TTD database showed that the target genes of LA, PPARG, and PTGS2 were related to the occurrence and development of bladder cancer (as shown in the black box)." (PMID 35656081, 2022). "PTGS2 or cyclooxygenase 2 (COX2) was found to be positive in 60% (368/617) of bladder cancer tissue." (PMID 22013484, 2011). "Moreover, qRT-PCR analysis showed that the mRNA expression of PPARG and PTGS2 was up-regulated in two bladder cancer cell lines in comparison with the normal cells SV-HUC-1." (PMID 35656081, 2022). "SZY-200 could down-regulate the expressions of PPARG and PTGS2 which were related to the occurrence and development of bladder cancer." (PMID 35656081, 2022). "The results showed that compared with normal tissues, ESR1, PTGS2 and BCL2 in bladder cancer tissues were significantly down-regulated; CASP3, INS, SRC, CDK4, GSK3B and ERBB2 were significantly up-regulated." (PMID 41287122, 2025). "In addition, LA alone could inhibit the proliferation of bladder cancer cells, while SZY-200 downregulates the expressions of the peroxisome-proliferator-activated receptor gamma (PPAR-γ) and prostaglandin-endoperoxide synthase 2 (PTGS2) genes involved in the development of bladder cancer." (PMID 40863333, 2025). "Our analysis confirmed the novel function of UCA1 in bladder cancer and provided another potential mechanism that UCA1 may compete with miR-143 to regulate the expression of MMP13 and PTGS2, both of the coding genes were identified here as dysregulated but lack fully elucidation in bladder cancer." (PMID 27863388, 2016).
cervical carcinoma (30 papers, 2002 to 2025). A carcinoma arising from either the exocervical squamous epithelium or the endocervical glandular epithelium. "Several of these proteins are implicated in cervical cancer, including Ptgs2 (up), Hmox1 (up), Mkl1 (down), and Arhgap5 (down) (60, –, 63)." (PMID 41165329, 2025). "Among the model genes, PTGS2 turned out to be the hub-gene with its function as a risk factor in cervical cancer." (PMID 35432535, 2022). "Prostaglandin-endoperoxide synthase 2 (PTGS2) expression is also epigenetically derepressed in cervical cancer by loss of miR-101 expression." (PMID 24551595, 2014). "Several signaling mechanisms for regulating PTGS2 in cervical cancer have been validated, including the EGF and nuclear factor κB (NF-κB) pathways, and PAR2 through an EGFR-dependent mechanism." (PMID 36765810, 2023). "PTGS2 over-expression has been considered as an indicator of invasiveness, aggressiveness, and metastatic potential in different malignancies including cervical carcinoma." (PMID 35736434, 2022). "Our laboratory and others have demonstrated elevated expression of PTGS1, PTGS2, the E-series prostanoid receptors PTGER2 and PTGER4 together with enhanced biosynthesis and signaling of PGE2 in cervical carcinomas." (PMID 22442729, 2012). "For example, rearrangements of chromosome 5, especially 5p gain, are often related to cervical cancer, and a miRNA located at 5p13.3, miR-579, is predicted to target the genes PTGS2 and IRF1, which are involved in cervical cancer." (PMID 20567512, 2010). "We have previously shown that PTGS1, PTGS2, PTGER2 and PTGER4 are elevated in cervical cancers." (PMID 22442729, 2012). "This work aimed to investigate the antitumor effect of piperine on cervical cancer and to determine whether this effect is modulated by the cyclooxygenase 2 (PTGS2) pathway using in vitro model of cervical cancer (HeLa, SiHa, CaSki), and non-tumoral (HaCaT) cell lines." (PMID 36678600, 2023).
non-small cell lung carcinoma (29 papers, 2002 to 2025). A group of at least three distinct histological types of lung cancer, including non-small cell squamous cell carcinoma, adenocarcinoma, and large cell carcinoma. "The PTGS2 gene plays a role in a number of pathological processes, including non-small cell lung cancer chemoresistance." (PMID 37764733, 2023). "For example, in non-small cell lung cancer uSTAT6 upregulates the cyclooxygenase 2 gene (PTGS2) through a consensus STAT6 site to provide protection against apoptosis." (PMID 34809691, 2021). "Prostaglandin-endoperoxide synthase-2 (PTGS2) promoted multidrug resistance in non-small cell lung cancer (NSCLC) cells." (PMID 31440159, 2019).
endothelial dysfunction (27 papers, 2011 to 2026). In vascular diseases, endothelial dysfunction is a systemic pathological state of the endothelium (the inner lining of blood vessels) and can be broadly defined as an imbalance between vasodilating and vasoconstricting substances produced by (or acting on) the endothelium. "However, this is less clear in the case of endothelial dysfunction, where following TNFα stimulation of HUVECs, carvedilol increased PTGS2 expression while bisoprolol decreased it." (PMID 34362171, 2021). "TNFα induced endothelial dysfunction also significantly increased mRNA levels of IL-6, NLRP3 and PTGS2." (PMID 34362171, 2021).
epilepsy (23 papers, 2016 to 2026). A brain disorder characterized by episodes of abnormally increased neuronal discharge resulting in transient episodes of sensory or motor neurological dysfunction, or psychic dysfunction. "We used, as our primary readout, the well-established PTGS2 pathway, that is involved in both generation of seizures and progression of epilepsy." (PMID 40848130, 2025). "As a readout, the effect of the drug was assessed on Ptgs2 and Tnf-α levels, whose levels have been studied in the context of epilepsy." (PMID 40848130, 2025). "In this research, we identified six characteristic genes associated with ferroptosis in epilepsy: NFE2L2, PTGS2, IL6, JUN, HMOX1, and TLR4." (PMID 37946105, 2023). "We have identified six feature genes (IL6, PTGS2, HMOX1, NFE2L2, TLR4, and JUN) strongly associated with ferroptosis in epilepsy, suggesting their potential as biomarkers for the diagnosis of temporal lobe epilepsy." (PMID 37946105, 2023). "Through the transcriptome analysis of the gene expression in hippocampus, Egr3, Nrg, Arc, and Ptgs2, closely related to epilepsy, had been proved to be downregulated by application of Dingxian pill." (PMID 31011358, 2019). "Based on the present results, ferroptosis-related hub genes NFE2L2, PTGS2, IL6, JUN, HMOX1, and TLR4 have good diagnostic value for epilepsy and may be potential early biological diagnostic targets." (PMID 37946105, 2023). "Consistent with our findings, we observed abnormal expression of ferroptosis‐related proteins ACSL4, PTGS2, and GPX4 in the hippocampal tissues of KA‐induced epileptic mice, indicating the involvement of ferroptosis in epilepsy." (PMID 39957487, 2025). "In the present study, we demonstrated that PTGS2, ESR1, MAPK1, PTPN11, and MAPK3 may be the targets of linoleic acid against epilepsy." (PMID 36034878, 2022).
ischemic stroke (23 papers, 2017 to 2025). A stroke disorder caused by obstruction of blood flow to the brain, due to thrombotic (local blood clot formation) or embolic (due to a blood clot or other material traveling from another site) event. "PTGS2 has been shown to reduce neurological damage caused by ischaemic stroke via the NF-kappa B axis." (PMID 40137146, 2025). "Several studies have now associated PTGS2 expression and activity with ischemic stroke, where its high expression promotes inflammation." (PMID 34898370, 2021). "By the bioinformatic analysis, three ferroptosis-related biomarkers are found as potential diagnostic biomarkers for ischemic stroke, namely, PTGS2, MAP1LC3B, and TLR4, which are upregulated in ischemic stroke and provide more evidence about the important role of ferroptosis." (PMID 35264947, 2021). "The silencing of PTGS2 has a similar protective effect against ischemic stroke in mice, promoting the angiogenesis of endothelial progenitor cells." (PMID 40149697, 2025). "Twelve genes have been reported as potential regulators of HT in ischemic stroke in previous studies: Casp3, Csf2, Ctnnb1, Cxcl12, Hif1a, Il1b, Mtor, Ptgs2, Ptprc, Tlr2, Tlr4, and Vcam1." (PMID 40002863, 2025). "A Multi-omics and network pharmacology study proved that PTGS2 was a common gene in thrombosis induced by ischemic stroke." (PMID 41415585, 2025). "Silencing the expression of PTGS2 plays an important role in angiogenesis and inhibits apoptosis, so PTGS2 can be used as a therapeutic target for ischemic stroke." (PMID 39519172, 2024). "Of note, specific knockdown of Ptgs2 expression in a mouse model of stroke provided neuroprotection in ischemic stroke by inhibiting apoptosis and promoting proliferation, migration and angiogenesis of endothelial precursor cells." (PMID 36818562, 2023). "For example, 31348992 Intersection analysis between DZXXI's putative targets with ischemic stroke-associated genes identified two important targets (PTGS1, PTGS2)." (PMID 34325669, 2021). "For example, genetic deletion of Ptgs2 or post-ischemic treatment with its inhibitor significantly reduced ischemic stroke injury." (PMID 34944656, 2021). "All in all, our results suggested MAP1LC3B, PTGS2, and TLR4 as potential diagnostic biomarkers for ischemic stroke, providing more evidence about the vital role of ferroptosis in ischemic stroke." (PMID 34707562, 2021). "The expression and diagnostic value of MAP1LC3B, PTGS2, and TLR4 in ischemic stroke were also verified using GSE22255." (PMID 34707562, 2021). "Several studies have investigated the association of a functional polymorphism of PTGS2 rs20417 and TXA2R rs1131882 with the risk of cardiovascular disease or ischemic stroke." (PMID 28704403, 2017). "The specific knockdown of PTGS2 can inhibit NF-κB signaling pathway, thus inhibit apoptosis, promote the proliferation, migration and angiogenesis of endothelial progenitor cells, and protect ischemic stroke mice." (PMID 34992531, 2021). "Moreover, the ROC diagnostic accuracy of MAP1LC3B, PTGS2, and TLR4 was 71.75, 68.26, and 53.25%, respectively, further confirming the diagnostic value of three ferroptosis-related biomarkers in ischemic stroke." (PMID 34707562, 2021). "However, the association of ICAM1 and PTGS2 expression with sex differences in ischaemic stroke has not been previously reported." (PMID 34792838, 2022). "The frequencies of PTGIS (rs5602CC) and PTGS2 (rs20417CC) variants were significantly higher in patients with carotid plaque compared with patients without plaque, and are associated with carotid plaque vulnerability, platelet activation and TXA2 levels in ischemic stroke patients." (PMID 31539405, 2019). "Among them, PTGS2 (COS-2) has been widely described as a key angiogenesis mediator and involved in BBB disruption in the context of ischemic stroke." (PMID 35163822, 2022).